BCL2 (BCL2 apoptosis regulator)
Diseases named in the same sentence as BCL2 in open-access papers (continued):
Sharing a sentence is not in itself a finding about the gene and the disease.
infarction (15 papers, 2013 to 2025). A localised pathological necrosis of tissue resulting from obstruction of the blood supply usually by a thrombus, an embolus, or vascular torsion. "Different outcome indexes were observed, and the most frequently used indicator was neurological severity score (in 19 studies); others included cerebral infarct size, cerebral edema volume, Bcl-2, Bax, VEGF, AKT, p-AKT, IL-6, SOD, and so on." (PMID 36637472, 2023). "Western blotting assay was used to detect the protein levels of p-53, NF-κB, Bcl-2, Bax, and Caspase-3 in the brain tissues surrounding infarction lesion." (PMID 35136538, 2022). "Increasing Bcl-2 expression in brain can reduce cerebral infarct volume by protecting neurons surrounding the ischemic focus (penumbra)." (PMID 24455679, 2013). "Moreover, apoptosis-related proteins (Bax, Bcl2, and cleaved caspase 3) were evaluated in the peri-infarction region." (PMID 38058609, 2023). "In addition, a research has found that GJ extracts could induced the protein Akt and Bcl-2 expression and inhibited cardiomyocytes death of in the infarcted hearts, which may conducive to the increased livability of the viable myocytes at risk after infarction." (PMID 30538763, 2018). "Among the predicted target genes was B-cell lymphoma 2 (Bcl-2), which plays a critical role in the inhibition of apoptosis, Bcl-2 expressed in myocytes of the human heart with infarction and participates in the protection or acceleration of cellular damage after infarction." (PMID 28693530, 2017). "The results of this study demonstrated that moxibustion can improve neurological dysfunction, decrease infarction area and neuronal apoptosis, downregulate the expression of NR2B and JNK, increase the level of Bcl-2, and decrease the level of caspase-3." (PMID 34733340, 2021).
memory impairment (15 papers, 2011 to 2025). "Previous studies have shown that STZ-induced memory impairment is associated with decreased Bcl-2 expression and Bcl-2/Bax ratio." (PMID 35464765, 2022). "LPS-induced memory impairment is associated with decreased Bcl-2 expression and increased neural cell apoptosis." (PMID 31747905, 2019). "Moreover, treatment of ginsenoside Rg1 (10 mg/kg) or G1 (5 μg/kg), a GPR30 agonist, prevented BCAS-induced memory impairment and hippocampal neuronal loss and apoptosis and promoted the ratio of Bcl-2 to Bax expression in the hippocampus (after behavioral tests)." (PMID 34899899, 2021). "To investigate the relationship between memory impairment and apoptosis, we studied representative apoptotic molecules of mitochondrial pathways, bcl-2, bax protein and caspase 3, 8 and 9 proteins." (PMID 21299906, 2011). "Furthermore, chronic use of curcumin was associated with an inhibition of apoptotic markers and an increase in Bcl-2, indicating a rescue against neurodegeneration and memory impairment that was confirmed through Nissl staining and FJB of neuronal cells." (PMID 39203857, 2024). "Strawberry and selenium, when administered individually, significantly attenuated memory impairment, oxidative stress, neuroinflammation, and apoptosis, as evidenced by marked normalization of Nrf2/HO-1, TAC, SOD, MDA, TLR4/NF-κB/TNF-α, NLRP3/CASP-1/IL-1β, and BAX/Bcl-2 signaling." (PMID 41471381, 2025).
myeloid malignancies (15 papers, 2016 to 2026). "The therapeutic efficacy of HMAs for myeloid malignancies is unsatisfactory in most cases, and adjuvant therapies with HMAs have been explored, such as the BCL-2 inhibitor venetoclax." (PMID 39198387, 2024). "The recent approval of a BCL-2 inhibitor venetoclax in combination therapy for myeloid malignancies likely justifies this direction of drug discovery." (PMID 38627844, 2024). "Bcl-2 inhibitors (eg, venetoclax) were first reported to inhibit the proliferation of malignant lymphocytes and have a significant effect on patients with chronic lymphoblastic leukemia, but research on myeloid tumors is relatively delayed." (PMID 33578607, 2021). "The recent success of the Bcl-2 inhibitor venetoclax in lymphoid and myeloid malignancies illustrates how found combinations may be of interest for future experiments." (PMID 30555636, 2018). "Venetoclax (VEN), a selective BCL-2 inhibitor predominantly metabolized by CYP3A4, is a cornerstone therapeutic for myeloid neoplasms (MNs)." (PMID 41915767, 2026). "What is noteworthy is that MYC rearrangement is found not only in BL and HGBL with MYC and BCL2 and/or BCL6 rearrangements but also in DLBCL, FL, PBL, B-LBL/ALL, and even in myeloid tumors." (PMID 37182167, 2023). "In preclinical studies, BCL-2 and SRC inhibitors have been shown to eradicate senescent myeloid tumor cells and have already been tested in AML." (PMID 33557090, 2021). "Evidence for BCL2 inhibition in this setting is limited to anecdotal reports, including a recent case describing prolonged disease control with ruxolitinib plus venetoclax in a BCR::JAK2-rearranged myeloid neoplasm, suggesting potential synergistic activity of JAK2 and BCL2 blockade." (PMID 41530508, 2026). "Hypomethylating agents such as decitabine and azacitidine with or without the BCL-2 inhibitor venetoclax rarely lead to long-term disease control in myeloid neoplasms, thus the addition IRAK-4 inhibition may deepen and prolong responses in patients with myeloid malignancies." (PMID 37954584, 2023).
osteoarthritis (15 papers, 2013 to 2025). A noninflammatory degenerative joint disease occurring chiefly in older persons, characterized by degeneration of the articular cartilage, hypertrophy of bone at the margins and changes in the synovial membrane. "The senescence‐associated miRNA mir‐34a, which is known to target Wnt and Notch pathways as well as the cell survival factors Sirt1 and Bcl2, is detected in EVs from human and animal subjects with muscle atrophy, bone loss, and osteoarthritis." (PMID 36398109, 2022). "It has been reported that TRAF-6 and BCL-2 proteins are closely associated with inflammatory disorder, such as osteoarthritis." (PMID 34550907, 2021). "This study demonstrates that a therapeutic-grade exosome formulation can alleviate osteoarthritis by restoring the balance between autophagy and apoptosis through modulation of the BCL2–Beclin-1 signaling axis." (PMID 41351157, 2025). "Upregulation of ciRS-7 promoted Bcl-2 expression to inhibit apoptosis, which was also reported in osteoarthritis (OA) model cells." (PMID 33957927, 2021). "Compared with osteoarthritis patients (OA), proapoptotic Bax was shown to be decreased, and antiapoptotic Bcl-2 was increased in FLS from RA patients." (PMID 31929822, 2019). "The pro-apoptotic Bax is decreased and anti-apoptotic Bcl-2 is increased in FLSs from RA patients compared with those from patients with osteoarthritis (OA)." (PMID 23421940, 2013). "This study aimed to investigate whether a therapeutic-grade purified exosome system derived from human plasma can modulate autophagy through regulation of BCL2 signaling, reduce chondrocyte apoptosis, and prevent osteoarthritis progression." (PMID 41351157, 2025). "The findings clearly suggested that MAPK and NF-κB pathways may be responsible involving the TRAF-6 and BCL-2 genes which might contribute for the ameliorative potential of RT in osteoarthritis induced chondrocytes." (PMID 34550907, 2021). "We determined the interleukin 6 (IL-6), IL-6 receptor α (IL-6Rα), gp130, receptor activator of nuclear factor κB ligand (RANKL), matrix metalloproteinase 3 (MMP3), TIMP metallopeptidase inhibitor 1 (TIMP1), and Bcl-2 levels in RA and osteoarthritis (OA) serum and synovial fluid." (PMID 29755657, 2018). "Moreover, the Bcl-2/Bax ratio may be a differentiator for human osteoarthritis (AUC = 0.673)." (PMID 36699321, 2022). "Levels of both BCL-2 and TRAF-6 proteins are elevated in inflammatory disorder conditions such as osteoarthritis and rheumatoid arthritis." (PMID 34550907, 2021).
T-cell leukemia (15 papers, 2008 to 2025). A malignant disease of the T-lymphocytes in the bone marrow, thymus, and/or blood. "Beyond that, data in Jurkat T cell leukemia cells suggest that radiogenic activity of IK channels is under the tight control of anti-apoptotic proteins such as Bcl-2." (PMID 32390841, 2020). "A study also showed that Vav1 plays a unique role in T-cell leukemia survival by selectively triggering the Rac2-Akt axis and elevating the expression of anti-apoptotic Bcl-2." (PMID 28029655, 2017). "However, the combination of bortezomib and rhTRAIL resulted in a synergistic cytotoxic effect in Bcl-2-overexpressing T cell leukemia cells." (PMID 41180258, 2025). "The Bcl2 gene is often up-regulated in T-cell leukemia and lymphoma." (PMID 30886319, 2019). "Here, we analyzed the crosstalk between Bcl-2 and TRPM2 channels in T cell leukemia cells during oxidative stress as conferred by ionizing radiation (IR)." (PMID 26839633, 2016). "To determine whether BCL family can also facilitate gene editing in other cell lines, we tested the effects of BCL-XL, BCL2, and MCL1 in mouse ESCs, HEK293T (human embryonic kidney cells), K562 (human erythroleukemia cells), and Jurkat (T-cell leukemia) cells." (PMID 30239926, 2018). "It has also been shown that miR-181a repressed the expression of genes which play a role in thymocyte maturation, such as Bcl-2, CD69, and the T-cell receptor, and the members of the miR-181 family were found to be significantly overexpressed in T-cell leukemia in our study." (PMID 24955371, 2014).
basal cell carcinoma (14 papers, 2007 to 2026). A carcinoma involving the basal cells. "For instance, in a study on basal cell carcinoma, the Bcl-2 promoter was found to have seven potential Gli anchor points, which enable Gli proteins to regulate Bcl-2 activity through transcriptional regulation of the Bcl-2 promoter." (PMID 26716648, 2016). "Basal cell carcinoma cells consistently express high levels of the anti-apoptotic Bcl-2 protein, while transgenic animal models have demonstrated that both Bcl-2 and Shh pathway members can contribute to multi-step skin carcinogenesis in vivo." (PMID 19742123, 2009). "Gli-3 also inhibits Gli-1's ability to upregulate bcl-2 transcription in basal cell carcinoma." (PMID 17505514, 2007). "Immunohistochemistry revealed focally positive BerEP4, CD34-positive stroma, negative androgen receptor, and positive bcl-2, consistent with trichoblastoma and distinguishing the tumor from basal cell carcinoma." (PMID 42196849, 2026). "BCL-2 staining was positive in the periphery of the basaloid proliferation, which is typical of basaloid follicular hamartoma, and not in a diffuse pattern, which is typical of nevoid basal cell carcinoma." (PMID 19203369, 2009).
chronic lymphoid leukemia (14 papers, 2013 to 2025). "Previous reports indicate that the BCL2 inhibitor venetoclax causes a depletion of various (B, T and NK) circulating lymphocyte subsets after one year of treatment of patients with chronic lymphoid leukemia." (PMID 37623817, 2023). "GR also increases BIM and decreases BCL2 expression, pushing lymphocytic leukemia cells toward apoptosis." (PMID 40565600, 2025). "We decided to evaluate the AZD-7762/BCL-2 inhibitor combination further, as the US FDA has approved BCL-2 inhibitor venetoclax/ABT 199 for subsets of lymphocytic leukemia, and clinical trials are underway to evaluate CHK1 inhibitors." (PMID 31448050, 2019). "Similar induction of apoptosis by down-regulating Bcl-2 expression in lymphocytic leukaemia cell line CEM-C7H2 was achieved after the treatment with PADMA 28 (a herbal mixture of 28 plants including aerial part of Potentilla aurea)." (PMID 26284809, 2015). "ERK-mediated signals and Bcl-2 both inhibit radiation-induced changes in the mitochondrial membrane and the subsequent cell death in lymphocytic leukemia cells." (PMID 24147004, 2013). "Notably, ABT-199 (also called Venetoclax) was recently approved by the Food and Drug Administration as a first-in-class Bcl-2 inhibitor for combination treatments in chronic lymphoid leukemias where Bcl-2 is overexpressed." (PMID 33339173, 2020). "BCL2 protein inhibitor venetoclax (ABT-199) has been authorized by Food and Drug Administration for relapsed/refractory chronic lymphoid leukemia with 17p deletion." (PMID 31253168, 2019).
dementia (14 papers, 2015 to 2025). Loss of intellectual abilities interfering with an individual's social and occupational functions. "Studies have shown that NLRP3, pro-apoptotic Bcl-2-related X protein (BAX), and anti-apoptotic protein B-cell lymphoma-2 gene (Bcl-2) are closely associated with the development of dementia." (PMID 41255822, 2025). "Apoptosis plays an important role in dementia neuron loss, and Caspases and Bcl-2 protein families are central components of apoptotic." (PMID 38284892, 2024). "Dysregulation of the ERK1/2-CREB- Bcl-2 pathway has been implicated in numerous neurodegenerative conditions, such as dementia." (PMID 38632534, 2024). "Additionally, JNK pathway activation can regulate the levels of B-cell lymphoma-2 (Bcl-2) family proteins, such as the prototypical anti-apoptotic protein Bcl-2 and the pro-apoptotic protein Bcl2-associated X protein (Bax), which are abnormally expressed in the brains of those with dementia." (PMID 39050746, 2024). "A previous study indicated a notable increase in Bcl-2 expression following low-frequency rTMS in dementia rats." (PMID 39051213, 2024). "They reported that exercise training against defects in the brain in the aging process with dementia showed decreased Bax expression and increased Bcl-2 expression." (PMID 35096300, 2021). "Following TSD treatment, the mean optical density of Bcl-2 was higher than those of the dementia model group (P < 0.05)." (PMID 25821478, 2015). "Together, the interplay between Bax and Bcl-2 dictates whether a cell undergoes apoptosis, positioning them as crucial markers for evaluating neuroprotection in dementia models." (PMID 40775503, 2025). "The significant increase in the Bcl2/BAX ratio after treatment with the micellar resveratrol (10 mg/kg) indicated an anti-apoptotic effect in the experimental dementia model, suggesting that the micelles could improve resveratrol’s bioavailability." (PMID 39684486, 2024). "RVT and mRVT treatment at doses of 5 and 10 mg/kg significantly stimulated Bcl2 and suppressed BAX expression in the cortex and hippocampus of dementia animals." (PMID 39684486, 2024). "Furthermore, micellar resveratrol increased the cAMP-response element-binding protein expression in the cortex and hippocampus of rats as well as the Bcl2/BAX ratio, which indicated an anti-apoptotic effect in the experimental dementia model." (PMID 39684486, 2024). "Some authors have described indirect apoptosis pathways data in blood leucocytes in elderly and in patients with dementia (like less resistance to experimental apoptosis inducers; senescence of CD8+ T-cells; and increased expression of HLA-DR, CD95, and Bcl-2 in CD3+ lymphocytes)." (PMID 32824789, 2020).
diabetic cardiomyopathy (14 papers, 2013 to 2024). Diabetic cardiomyopathy is a disorder of the heart muscle in people with diabetes. "Compared with control mice, diabetic cardiomyopathy mice exhibited reduced cardiac Bcl-2 expression and increased Bax and cleaved caspase-3 expression, whereas pyridostigmine treatment ameliorated these alterations and reversed mitochondria-related apoptosis." (PMID 34084135, 2021). "In this report, STZ‐treated rat hearts displayed increased ratio of Bax/Bcl‐2 with increased expression of caspase‐3 and caspase‐9, indicating developed apoptosis via mitochondrial signaling pathways in diabetic cardiomyopathy." (PMID 29446246, 2018). "Resveratrol, carnosic acid, beta carotene, and curcumin can activate autophagy through the SIRT1/FOXO1/Rab7 axis, PI3K/Akt/mTOR, activate AMPK and JNK1, phosphorylated Bcl-2 and Bim and subsequently disrupted their interactions with Beclin1 to treat diabetic cardiomyopathy." (PMID 37810881, 2023). "A recent study also suggested that the dissociation of Bcl-2 from Beclin1 may be an important mechanism for preventing diabetic cardiomyopathy via AMPK activation that restores autophagy and protects against cardiac apoptosis." (PMID 24086665, 2013). "For instance, ATF4 in DCM promotes cardiac fibrosis and oxidative stress, while downregulation of Bmal1 induces mitochondrial dysfunction by promoting Bcl2/IP3R-mediated mitochondrial Ca2+ overload, leading to diabetic cardiomyopathy." (PMID 38664790, 2024). "Curcumin ameliorates diabetic cardiomyopathy by activating AMPK and JNK1, phosphorylated Bcl-2 and Bim and subsequently disrupted their interactions with Beclin1, promoting autophagy and attenuating apoptosis in vivo and in vitro diabetic models." (PMID 37810881, 2023). "Similarly, miR-410-5p is involved in the development of diabetic cardiomyopathy and regulates cardiomyocyte apoptosis by targeting PIM1 protein and its downstream protein Bcl-2/Bax." (PMID 38361743, 2024). "In another study on diabetic cardiomyopathy, it was reported that NKILA was highly expressed in high sugar-induced AC16 cells, and apoptosis protein markers such as BAX, CASP3, and CASP9 were increased, while anti-apoptosis protein BCL-2 was inhibited." (PMID 39184397, 2024).
laryngeal carcinoma (14 papers, 2005 to 2024). Carcinoma that arises from the laryngeal epithelium. "Radioresistant laryngeal cancer was associated with bcl-2 (P<0.001) and bcl-XL (P=0.005) expression and loss of bax expression (P=0.012) in pretreatment biopsies." (PMID 15928664, 2005). "Quercetin induced apoptosis in laryngeal cancer cells by inhibiting Akt/PKB phosphorylation and significantly decreasing anti-apoptotic Bcl-2 and Bcl-XL, thus acting as a chemosensitizer to cisplatin." (PMID 38177197, 2024). "miR-34c inhibits Bcl2 by binding to the 3′ untranslated region (UTR) of the Bcl2 gene, thus downregulating the viability of laryngeal cancer cells and inducing apoptosis." (PMID 35205390, 2022).
marginal zone lymphoma (14 papers, 2015 to 2026). A usually indolent mature B-cell lymphoma, arising from the marginal zone of lymphoid tissues. "Based on the activity observed in DLBCL and MCL cell lines, we also tested the compound in two marginal zone lymphoma (MZL) cell lines (Karpas1718 and VL51) and their derivatives with acquired resistance to PI3K inhibitors, BTK inhibitors, and BCL2 inhibitors." (PMID 40563683, 2025). "In addition, we previously demonstrated the diagnostic relevance of STMN1 for FLs including those that are BCL2 negative, and showed its potential usefulness in distinguishing FLs from marginal zone lymphomas (MZLs), which are usually STMN1 negative." (PMID 31686194, 2019).